CALR (calreticulin)
Diseases named in the same sentence as CALR in open-access papers (continued):
Sharing a sentence is not in itself a finding about the gene and the disease.
tumor (continued). "It was shown that patients with NSCLC (treated with RT only, N = 23) with high calreticulin expression in the tumor (N = 8), tended to have significantly better overall survival (OS) compared with RT-treated patients with NSCLC with low calreticulin expression (N = 15)." (PMID 33920544, 2021). "One of these proteins that has acquired a preponderant role as a modulator of the functions of the extracellular microenvironment is calreticulin (TcCRT), mediating the infectivity of the parasite to inhibit complement; it is also antiangiogenic and inhibits tumor development in vivo." (PMID 34572535, 2021). "However, the effect of CALR on tumor prognosis, its relationship with the immune system and the underlying mechanisms in pan-cancer has not been well characterized." (PMID 34910788, 2021). "Furthermore, the potential to increase tumor immunogenicity was assessed by analyzing Calreticulin translocation and immune relevant surface markers." (PMID 34063457, 2021). "This could explain the apparent lack of antibodies specific to mutant CALR, as circulating mutant CALR could neutralize the formed antibodies making these undetectable and additionally impede on the anti-tumor effect of the antibodies." (PMID 33718228, 2021). "However, given the location and function of CALR on stressed or dying cells, it remains questionable to what extent circulating CALR levels reflect the treatment-induced upregulation of CALR on the surface of tumor cells." (PMID 34944879, 2021). "As a potential target for tumor therapy, the expression of CALR in most tumors remains unclear and few studies have comprehensively analyzed the role of CALR in cancers." (PMID 34910788, 2021). "Anthracyclines such as DOX induce the characteristic signs of immunogenic cell death by triggering tumor signaling pathways that lead to the upregulation of calreticulin on the cell surface, prompting dendritic cell activation and subsequent antigen presentation." (PMID 33532588, 2021). "In addition to enabling the mobilization of T cells against cancerous cells, radiation results in the translocation of calreticulin to the tumor-cell surface." (PMID 33430362, 2021). "It is thought that high level of calreticulin and HMGB1 is associated with a more advanced tumor process and potentially could act as an unfavorable prognostic marker of disease." (PMID 33799560, 2021). "However, impaired tumor cells can generate DAMPs (such as calreticulin (CRT), high‐mobility group box 1 (HMGB1), and adenosine triphosphate (ATP)) by PDT‐induced immunogenic cell death." (PMID 33898169, 2021). "Calreticulin acts as an ‘eat me’ signal for DCs when exposed to the membrane resulting in enhanced phagocytosis of the cancer cells by DCs and, thus, results in an increased release of tumor-specific antigens (TSAs)." (PMID 34768644, 2021). "In addition, calreticulin neutralizes CD47 receptors on the tumor cell surface, and thereby, increases the tumor cell engulfment by macrophages." (PMID 33546172, 2021). "Therefore, we applied bioinformatics analysis to verify the possibility of CALR as an emerging and accurate tumor biomarker for targeted therapy." (PMID 34910788, 2021). "The spatiotemporal release of HSP70, calreticulin, HMGB1, and some other molecules, e.g., ATP or S100 proteins from tumor cells, are known as damage-associated molecular pattern (DAMP) signals that can promote the uptake, processing, and presentation of tumor antigens by DCs." (PMID 32872532, 2020). "Moreover, the tumor volume was significantly reduced in the CALR-silenced group compared to the control group." (PMID 33221760, 2020). "Thus, the CALR-activated dendritic cells have potent activity in priming anti-tumor cytotoxic CD8+ T lymphocytes (CTLs) and CALR is a potential molecular target in anti-tumor immunotherapy." (PMID 32082309, 2020).
tumor (continued). "These JX-infected, dying tumor cells released DAMPs, such as calreticulin and annexin A1, which are involved in the activation of DCs.41 42 Additionally, JX itself further induced the activation and maturation of DCs within TME because it was genetically engineered to secrete mGM-CSF." (PMID 33199510, 2020). "However, three works were published in which overexpression of calreticulin promoted EMT in different tumor cells." (PMID 32268506, 2020). "CALR expression level is considered as an important indicator of tumor prognosis." (PMID 32082309, 2020). "NcRNA-RB1 inhibits the expression of CALR, prevent tumor cells release “killing me” signal." (PMID 33194608, 2020). "The prominent mEHT-related upregulation and cell membrane accumulation of calreticulin after 12 h and Hsp70 after 48 h, accompanied by the nuclear-to-cytoplasmic Hmgb1 translocation and release from tumor cells from 48 h post-treatment, confirmed significant DAMP signaling." (PMID 32872532, 2020). "Furthermore, CALR-mediated phagocytosis enhances IFN-γ release in tumor-draining lymph nodes, and radiation and anthracycline therapies appear to depend on an intact T-cell response because T-cell–depleted mice do not respond to treatment." (PMID 32630667, 2020). "Tumor cells may also express molecules, such as surface calreticulin, tumor antigens or NKG2D ligands." (PMID 32733470, 2020). "In addition to enabling the mobilization of T-cells against cancerous cells with the help of released TAAs, radiation results in the translocation of calreticulin (CRT) to the tumor-cell surface." (PMID 31182960, 2019). "This process, known as immunogenic cell death, is characterized by a variety of tumor cell modifications, i.e., cell surface translocation of calreticulin, extracellular release of adenosine triphosphate and pro-inflammatory factors, such as high mobility group box 1 proteins." (PMID 31649875, 2019). "We localized calreticulin in tumor tissues using immunohistochemistry." (PMID 30974841, 2019). "To evaluate whether doxorubicin treatment induces calreticulin expression on MNNG/HOS tumor cells, we applied a calreticulin stain." (PMID 31376208, 2019). "This approach identified 4 different clusters of patients corresponding to high versus low CALR expression in the context of elevated versus reduced tumor infiltration by DC-LAMP+ mature DCs, CD20+ B cells and CD8+ T cells (ImmuneHi and ImmuneLo, respectively)." (PMID 31747968, 2019). "In particular, immune recognition-associated proteins with impact on tumor cell clearance through phagocytosis, such as CD47 and calreticulin, could contribute to adaptive resistance and immune escape." (PMID 32082304, 2019). "An increasing number of studies have demonstrated that CALR may be involved in the tumor initiation, progression, and metastasis, suggesting that CALR is a key therapeutic target in cancer." (PMID 31632490, 2019). "Moreover, little is known on the potential links between CALR levels and tumor infiltration by NK cells." (PMID 31747968, 2019). "Some key molecules, such as CALR, HLA-A, HLA-DRB1, PDIA3, HLA-DQB1, HLA-E, and TAP2, have been implicated in various types of cancers and emphasized their important values related to the tumor progression." (PMID 31258820, 2019). "It has been reported that NPS treatment of non-viral-transformed tumor cells results in the release of the three classical danger-associated molecular pattern molecules: calreticulin, ATP, and HMGB1, all associated with programmed cell death." (PMID 29324830, 2018). "In addition to HMGB1, calreticulin (CRC) has also been shown to be expressed on the surface of cells following RT leading to better anti-tumor immunity." (PMID 30692991, 2018). "By enhancing Ca2+-leakage-mediated ER stress, Klotho could increase the calreticulin exposure at the surface of tumor cells and so, facilitate immunogenic cell death." (PMID 30441794, 2018). "Tumor cells express the “eat me” signal calreticulin on their plasma membrane." (PMID 28589095, 2017).
tumor (continued). "Interestingly, stimulation through TLR-3, -4, and -7 has previously been reported to synergize with CD47 blockade on tumor cells by increasing secretion and cell-surface exposure of calreticulin on macrophages in a Btk-dependent manner." (PMID 29084248, 2017). "However, under conditions of extreme stress leading to ICD, as is often the case with tumor cells during chemotherapy, calreticulin can be translocated to the surface of dying cells." (PMID 29326711, 2017). "The expression was high in almost all malignant epithelial cells while inside the tumor stroma, high expression of calreticulin could be observed in spindle shaped cells of the stroma." (PMID 27418879, 2016). "However, calreticulin exposure of tumor cells after docetaxel treatment was observed which significantly enhanced tumor cell killing by antigen-specific CD8+ cytotoxic T cells." (PMID 31093338, 2016). "High miR-27a/low calreticulin was also associated with the development of liver metastasis and CD3+/CD8+ T cells' infiltrates were reduced in metastases compared with matched primary tumours." (PMID 26913609, 2016). "Hallmarks of immunogenic cell death include exposure of calreticulin on the tumor cell surface, which serves as an “eat-me” signal for dendritic cells and macrophages, and HSP90 exposure, which facilitates dendritic cell-tumor cell adhesion and stimulates dendritic cell maturation." (PMID 27515027, 2016). "During apoptosis, tumor cells express special molecules at their surface (lipid phosphatidylserine, oxidized PS, oxidized low-density lipoprotein and the multi-functional protein calreticulin) which are recognized by macrophages and lead to tumor cell phagocytosis." (PMID 27686848, 2016). "Our data demonstrate that an increased tumour/normal ratio of calnexin, but not calreticulin, was significantly associated with poor clinical outcome in patients that received chemotherapy." (PMID 27369741, 2016). "Thus, we assessed the translocation of Calreticulin (CRT) from the lumen of ER vesicles to the surface of tumor cells and the release of HMGB1, key hallmarks of ICD." (PMID 27028869, 2016). "However, the increase in CTL-mediated lysis was completely abrogated by the addition of calreticulin blocking peptide, demonstrating the importance of surface calreticulin in T-cell killing of tumor cells upon exposure to 223Ra." (PMID 27893426, 2016). "In the same work, the authors showed that tumor cells treated by a chemotherapy agent mitoxantrone not only translocated intracellular calreticulin to their surface but were also able to bind externally added calreticulin protein." (PMID 25692097, 2015). "The reported activation of ICD upon treatment with recombinant TRAIL suggests that calreticulin may regulate the pro-immunogenic effect of TRAIL during anti-tumor immunity." (PMID 25750898, 2015). "Recombinant calreticulin was found to bind to mouse SCCVII tumor cells treated by PDT." (PMID 25692097, 2015). "Hence, recognition of CALR on dying cells is an early event that leads to engulfment of dying tumor cells by APCs and promotes priming of the adaptive immune response." (PMID 26486085, 2015). "Accumulated evidences indicate that calreticulin has great impacts for the development of different cancers and the effect of calreticulin on tumor formation and progression may depend on cell types and clinical stages." (PMID 25918716, 2015). "It is currently unclear whether the injection of a fragment of recombinant calreticulin blocks tumor growth using these or other mechanisms." (PMID 25386408, 2014). "Radiation also caused a 6.5-fold increase in tumor cells with strong calreticulin expression relative to non-irradiated controls." (PMID 24480782, 2014). "Our results indicated that calreticulin correlated to tumor stage of ACC in clinical samples." (PMID 23587357, 2013).
tumor (continued). "Moreover, the ethanol-treated tumor cells expressed “eat-me” signals such as calreticulin (CRT) on the cell surface and released immunostimulatory factors such as heat shock protein (HSP)90α and high-mobility group box 1 (HMGB1)." (PMID 23717436, 2013). "Irradiation of tumors has been shown to impair on the one hand the immunosuppressive action of the tumor and on the other to induce so-called “immunogenic” cell death within the tumor with translocation of calreticulin to the plasma membrane, release of HMGB1 or ATP." (PMID 23966948, 2013). "BLM induces anti-tumor immunity which relies on calreticulin, CD8+ T cells and interferon-γ." (PMID 23762310, 2013). "Intra-tumoral injection with adenoviral vectors was performed to investigate whether Ad-CALR/MAGE-A3 had the effect of inhibition on tumor growth in vivo." (PMID 22293781, 2012). "Possible explanation might be that large fraction size induces translocation of cytosolic calreticulin to the cell surface that promotes phagocytosis of irradiated tumor cells by tumor infiltrating dendritic cells." (PMID 22666458, 2012). "Anti-tumor immunity conferred by purified calreticulin could derive from calreticulin-dependent delivery of intracellular antigens to relevant APCs." (PMID 22848581, 2012). "Following the drug administration, the intracellular protein calreticulin is translocated with an unknown mechanism onto the plasma membrane, where it triggers the phagocytosis of tumour cells by dendritic cells." (PMID 19925669, 2009). "Additionally, they might be used in conjunction with Azacitidine, which can upregulate the expression of calreticulin, an ‘eat me’ signal, on tumor cell surfaces." (PMID 40136470, 2025). "Furthermore, calreticulin induced by radiotherapy may be crucial in tumor cells uptake and enhancing immune cell activity." (PMID 40475019, 2025). "This specificity for tumors may be attributed to the expression of “eat-me” signals such as calreticulin, which can trigger phagocytosis by macrophages, leading tumor cells to be more reliant on expression of “Don’t eat me” signals such as CD47 to avoid being killed compared to healthy cells." (PMID 40078999, 2025). "Similarly, dying tumor cells can also express damage-associated molecular patterns (DAMPs), such as ER chaperone calreticulin (CRT/CALR) and heat shock protein (HSP), which attract and activate innate immune cells by binding to pattern recognition receptors (PRRs)." (PMID 38816871, 2024). "Moreover, splenic CLL cell ecto-CALR expression negatively correlated with splenic tumor percentage, suggesting that translocation of CALR to the cell membrane of CLL cells may play a role in their clearance following SpiD3 treatment." (PMID 39767763, 2024). "However, MoNoS operated at kINPen standard argon fluxes significantly improved cancer organoid growth reduction and increased tumor immunogenicity, as seen by elevated calreticulin and heat-shock protein expression, along with a significantly spurred cytokine secretion profile." (PMID 36831596, 2023). "Tumor cells also release damage-associated molecular patterns (DAMPs) after IR, including high-mobility group box 1 (HMGB1), heat shock proteins (HSPs), and calreticulin (CRT), which mediate phagocytosis of antigen-presenting cells (APCs) and initiate tumor-specific T cell activation." (PMID 37600785, 2023). "Specifically, some dying tumor cells release multiple danger signals or damage-associated molecular patterns (DAMPs), including high mobility group protein B1 (HMGB1), calreticulin and ATP, which dominantly represent immunogenic features and may contribute to the immunotherapy." (PMID 37553698, 2023). "Meanwhile, the expression of MYH9, FN1, LTBP1, CALR and AKAP12 is effective in discriminating HR-NB from LR-NB patients, indicating that these non-invasive biomarkers may be used to detect patients at risk of developing aggressive tumor phenotypes." (PMID 37947594, 2023).
tumor (continued). "Additionally, calreticulin (CALR) was over‐expressed in 19% of tumor samples." (PMID 36464833, 2023). "Thus, released and/or circulating levels of CALR may reflect the local treatment-induced changes of CALR expression on the tumor cell level." (PMID 34944879, 2021). "Tumor cells release specific proteins that are characteristic of ICD and feature as danger signals, or DAMPs (danger-associated molecular patterns) including calreticulin (CRT), extracellular adenosine triphosphate (ATP), heat shock protein (HSP), and high mobility group protein B1 (HMGB1)." (PMID 34771120, 2021). "In addition, this nanoparticle also triggered cell surface exposure of CALR, as well as an abscopal effect in tumor-bearing mice, which likely increased the efficacy of ICIs through a more important recruitment of CD4+ and CD8+ cytotoxic T-cell populations in the tumors." (PMID 34834202, 2021). "In addition, the expression of calreticulin (CRT) on the surface of the tumor cells is increased." (PMID 33799560, 2021). "Moreover, the systematic assessment of ICD biomarkers such as the expression of CALR or HMGB1 on tumor biopsies may yield useful information for patient stratification." (PMID 33243969, 2020). "After irradiation, tumour cells can undergo a form of cell death known as immunogenic cell death and express damage-associated molecule patterns (DAMP) or “danger signals”, which includes exposure of calreticulin, the extracellular release of ATP and high mobility group box 1 (HMGB1) and uric acid." (PMID 33008040, 2020). "It is well accepted that IR can induce immunogenic cell death, resulting in pro-phagocytic signals exposure to the tumor cell membrane (calreticulin, phosphatidylserine and so on), which may be very conducive to enhancing macrophage-dependent phagocytosis of CD47 blockade." (PMID 33020240, 2020). "Given the specificity and reported high frequencies of the JAK2V617F, MPL and CALR mutations in this group of neoplasms, the diagnosis of these diseases should not be made on clinical and hematological characteristics alone but should include genetic screening of patients." (PMID 31208359, 2019). "It means that CALR may promote tumor angiogenesis, accelerate tumor invasion and metastasis." (PMID 31632490, 2019). "In addition to 3-BrPA, ER stress-inducing agents such as bortezomib, oxaliplatin, and oncolytic virus also induce ER stress to induce immunogenic cell death by expressing DAMP signals (e.g. calreticulin) on the cell surface, thereby activating the immune system of the tumor microenvironment." (PMID 31133013, 2019). "However, CALRHi/CD8Hi patients had a robust survival advantage over their CALRLo/CD8Hi counterparts (p = 0.001), indicating that CALR expression can be employed to identify HGSC patients with extensive tumor infiltration by CD8+ T cells but relatively poor disease outcome." (PMID 31747968, 2019). "Furthermore, knockdown of calreticulin would impair the T cell recognition of tumor cells." (PMID 30115069, 2018). "Thus we next evaluated the expression levels of BOK protein and the key ER stress markers 78 kDa glucose-regulated protein/binding immunoglobulin protein (GRP78), heat shock protein 90 kDa beta member 1 (GRP94) and Calreticulin in fresh-frozen tumour resections of CRC patients." (PMID 29374142, 2018). "Indeed, macrophages can release apoptosis-inducing soluble factors, such as nitric oxide (NO) and TNFα, exert phagocytosis based on the expression of signal molecules on the surface of tumours cells, such as phosphatidylserine and calreticulin, and clear viable antibody-coated tumour cells." (PMID 28404796, 2017). "Calreticulin surface exposure and ER stress have previously been linked in immunogenic modulation studies of EBRT, which led us to investigate whether 223Ra also induces ER stress in tumor cells." (PMID 27893426, 2016). "Calreticulin accumulated on the surface of tumor cells may modulate their death." (PMID 25692097, 2015).